CFTR (CF transmembrane conductance regulator)
Diseases named in the same sentence as CFTR in open-access papers (continued):
Sharing a sentence is not in itself a finding about the gene and the disease.
cystic fibrosis (continued). "These experiments demonstrate that these anionophores could be used to promote chloride and bicarbonate transport in cells, i.e., are good candidates to replace the defective or missing CFTR in an attempt to design a new cystic fibrosis therapy, as proposed for other anion transporters." (PMID 30131695, 2018). "Canonical PDZ interactions play important roles in the intracellular trafficking of cystic fibrosis transmembrane conductance regulator (CFTR)." (PMID 29472314, 2018). "Recently, the role of miRNAs as therapeutic targets and in regulating cystic fibrosis transmembrane conductance regulator (CFTR) expression has been a topic of increasing interest to the CF research community." (PMID 28263989, 2017). "Therefore, low expression of Tcf4 (as it occurs in cystic fibrosis) might lead to low transcription of the CFTR gene and high miR-145-5p dependent down modulation of CFTR mRNA." (PMID 29286300, 2017). "Dysfunction of cystic fibrosis transmembrane conductance regulator (CFTR) has been shown to result in inflammatory responses in cystic fibrosis patients." (PMID 28615349, 2017). "Cystic Fibrosis is an autosomal recessive genetic disease which results in dysfunction of the CF transmembrane conductance regulator (CFTR) protein." (PMID 28959210, 2017). "The cystic fibrosis transmembrane conductance regulator (CFTR) is responsible for the disease cystic fibrosis." (PMID 27734094, 2017). "The disease is caused by mutations in the cystic fibrosis transmembrane conductance regulator (CFTR) gene, which produces a dysfunctional ion channel in CF patients and results in multiple sequelae." (PMID 29190650, 2017). "Since the discovery of the Cystic Fibrosis Transmembrane Regulator (CFTR) gene in 1989, more than 2000 mutations have been detected and reported in the CFTR1-database (CF Mutation Database)." (PMID 28830496, 2017). "The Cystic Fibrosis Transmembrane Conductance Regulator (CFTR) gene, causing CF, was identified in 1989 and located on chromosome 7q31.2, spanning a transcription unit of about 216.7 kb with 27 exons." (PMID 28339466, 2017). "Furthermore, with the advent of recent innovations and improvements to cryo-EM-based techniques, the structure of CFTR was recently solved, paving the way for subsequent structure-based drug development of the next generation of more effective Cystic Fibrosis therapies." (PMID 28409029, 2017). "Cystic fibrosis, Online Mendelian Inheritance in Man (OMIM) #219700, is a life-threatening autosomal recessive monogenetic disease caused by mutations to the cystic fibrosis transmembrane conductance regulator (CFTR) gene (OMIM #602421)." (PMID 28196530, 2017). "Mutation scanning methods in Cystic Fibrosis Transmembrane Conductance Regulator (CFTR) gene may not distinguish between a Cystic Fibrosis causing mutation and a benign variant." (PMID 28545452, 2017). "Over 2000 mutations in the cystic fibrosis transmembrane conductance regulator (CFTR) gene have been identified in patients with CF, which partly explains their varied response to treatment." (PMID 28649446, 2017). "Therefore, our data suggest that cystic fibrosis, Barrett's oesophagus, and oesophageal adenocarcinoma might have a common pathophysiological feature of gastro-oesophageal reflux, with CFTR playing an important part in this process." (PMID 27527254, 2016). "In addition, CFTR gene analysis might be also helpful to evaluate the presence of latent cystic fibrosis." (PMID 27597925, 2016). "Cystic fibrosis is a complex genetic disease, affecting multiple organs through the disruption of the CF transmembrane conductance regulator protein." (PMID 26968039, 2016). "Definitions and nomenclatures have been revisited and new CF phenotypes have been recognized, e.g. cystic fibrosis transmembrane conductance regulator (CFTR)-related disorders and CFTR-related metabolic syndrome." (PMID 26668678, 2016).
cystic fibrosis (continued). "To test this hypothesis, we expressed either wild-type CFTR or the adenylate kinase-deficient Q1291F mutant in well differentiated primary human airway epithelia from cystic fibrosis patients (that lack endogenous CFTR activity) because they are closest to an in vivo airway epithelium." (PMID 25887396, 2015). "A cystic fibrosis transmembrane conductance regulator knockout (CFTR-/-) pig that displays most of the features of the human CF disease has been recently developed." (PMID 26600426, 2015). "The cystic fibrosis model is an example of genetically engineered pigs created by targeted inactivation of the cystic fibrosis transmembrane conductance regulator (CFTR) gene." (PMID 26442109, 2015). "It has been fully established that cystic fibrosis transmembrane conductance regulator (CFTR) and calcium-activated chloride channels (CaCCs) are the main chloride channels present in the luminal membrane of enterocytes." (PMID 26635857, 2015). "Further studies will need to clarify whether the local application of gentamycin in addition to the antimicrobial effect corrects the translation of CFTR gene in cystic fibrosis patients with premature stop codons in vivo and affect the (local) disease progression." (PMID 26770278, 2015). "Over 1,900 mutations have been reported in the cystic fibrosis transmembrane conductance regulator (CFTR), the gene that is defective in CF patients." (PMID 25853698, 2015). "Delivery of non-CFTR encoding plasmid DNAs to the human airways has not been associated with a gain in CFTR chloride-channel function, nor improvement in any cystic fibrosis-related assay, and plasmid DNA is generally associated with pro-inflammatory, rather than non-specific, beneficial effects." (PMID 26149841, 2015). "Cystic fibrosis is a genetic disease resulting from dysfunction of the CF transmembrane conductance regulator (CFTR)." (PMID 25622042, 2015). "Therefore, the low detection rate can provide not highly informative first level cystic fibrosis screening assay, above all in absence of family risk situations, such as in case of patients who require CFTR genetic testing before IVD procedure." (PMID 25922769, 2015). "Cystic fibrosis (MIM219700) is a life shortening, monogenic condition caused by mutations in cystic fibrosis transmembrane conductance regulator (CFTR)." (PMID 26047157, 2015). "Like humans with cystic fibrosis, the CFTR(−/−) ferrets develop severe lung and gastrointestinal disease and thus serve as a highly relevant model for unraveling CF pathophysiology." (PMID 24594704, 2014). "However, we discovered 9 CFTR mutations that do not cause cystic fibrosis but do cause inflammation and scarring of the pancreas (chronic pancreatitis)." (PMID 25033378, 2014). "Mutations to the CFTR gene that do not cause cystic fibrosis have been considered benign." (PMID 25033378, 2014). "Cystic fibrosis is diagnosed based on a defined clinical phenotype and confirmation of cystic fibrosis transmembrane regulator (CFTR) dysfunction, commonly demonstrated by a sweat chloride value of ≥ 60 mmol/l and/or detection of two CF-causing mutations." (PMID 25280757, 2014). "In the lung, the two major inherited genetic disorders, cystic fibrosis and AAT deficiency, are conformational disorders that are caused by the hereditary expression of mutant alleles of the cystic fibrosis transmembrane conductance regulator (CFTR) and AAT, respectively." (PMID 26567105, 2014). "In fact, CF liver disease depends on the altered activity of cystic fibrosis transmembrane regulator (CFTR) chloride channel on the apical membrane of cholangiocytes." (PMID 25132997, 2014).
cystic fibrosis (continued). "CFTR is a predicted target of miR-101 and miR-144, and this group further demonstrated that cadmium upregulates the expression of miR-101 and miR-144, suggesting that cadmium, through miRNA induction, may be involved in the pathogenesis of cystic fibrosis." (PMID 25076963, 2014). "However, the effects of low serum IGF-1 on the cystic fibrosis transmembrane conductance regulator (CFTR), whose defective function is the primary cause of cystic fibrosis, have not been studied." (PMID 23555857, 2013). "Cystic fibrosis is a severe and diffuse recessive genetic disease due to defects of the CF transmembrane conductance regulator (CFTR) gene." (PMID 23935691, 2013). "In the CF lung, a failure in the Cl channel CFTR (Cystic Fibrosis transmembrane conductance regulator) produces salt imbalances that allow thick mucus to develop." (PMID 23409004, 2013). "Thus, whereas the penetrance of the most common CFTR gene lesion, ΔPhe508 (rs113993960), in cystic fibrosis is very high, the penetrance of the CFTR Arg117His (rs78655421) mutation (in any allele combination) appears to be so low as to call into question its putative role as a pathological mutation." (PMID 23820649, 2013). "Treatments designed to correct cystic fibrosis transmembrane conductance regulator (CFTR) defects must first be evaluated in preclinical experiments in the mouse model of cystic fibrosis." (PMID 23505426, 2013). "In PBMC from cystic fibrosis patients, the mature F508del-CFTR is almost undetectable and levels of the split channel form are higher than those detected in control cells." (PMID 23785472, 2013). "CFTR, the protein defective in Cystic Fibrosis, is a large transmembrane protein belonging to the ATP-binding cassette (ABC) transporter superfamily." (PMID 24086355, 2013). "Cystic fibrosis, which is the most common lethal monogenetic disease, results from the absence of a functional cystic fibrosis transmembrane conductance regulator (CFTR) protein." (PMID 22937069, 2012). "The most common cystic fibrosis manifestation is the progressive chronic obstructive pulmonary disease caused by deficiency, dysfunction, or absence of the CFTR (Cystic Fibrosis Transmembrane Regulator) protein on the apical surface of the cells in the respiratory tract." (PMID 22950544, 2012). "In particular, in the case of cystic fibrosis, MPs have a potential application in nongenic, cell-to-cell autologous transfer of human mRNAcftr and the restoration of the normal chloride channel function in CFTR-deficient cells." (PMID 23284987, 2012). "Mutations in the gene-encoding cystic fibrosis transmembrane conductance regulator (CFTR) cause defective transepithelial transport of chloride (Cl−) ions and fluid, thereby becoming responsible for the onset of cystic fibrosis." (PMID 22514656, 2012). "Thus, despite differential selective pressure that these distantly related ABC transporters have been subjected to, the cellular context in terms of interacting proteins that govern the biogenesis of Yor1 and CFTR is conserved and renders yeast a useful and powerful model for cystic fibrosis." (PMID 23270647, 2012). "Mutation in cystic fibrosis transmembrane conductance regulator (CFTR), located on the long arm of chromosome 7 (7q21-34) causes CF (-)." (PMID 24551767, 2012). "One of these channels, cystic fibrosis transmembrane conductance regulator (CFTR), is a well-known example in which defective mutations cause cystic fibrosis characterized by abnormal airway mucus." (PMID 22731784, 2012). "In addition, much attention is focused on cystic fibrosis, a hereditary disease of chloride ion channels (cystic fibrosis transmembrane conductance regulator (CFTR)) accompanied by pancreatic fibrosis together with functional defects of the lungs and the small intestine." (PMID 22133269, 2011).
cystic fibrosis (continued). "Dysfunction of the CF neutrophil occurs both as a result of the intense inflammatory and proteolytic milieu within the CF airway, and as a direct result of decreased cystic fibrosis transmembrane conductance regulator (CFTR) expression within the cell." (PMID 21909403, 2011). "Since the discovery of the human CFTR gene in 1989 various mouse models for cystic fibrosis have been generated and used as a very suitable and popular tool to approach research on this life-threatening disease." (PMID 22059807, 2011). "We here present a flow cytometric procedure to study CFTR expression in human primary nasal epithelial cells from patients with Cystic Fibrosis." (PMID 22163268, 2011). "Phagocytic killing of P. aeruginosa by CF neutrophils is impaired due to decreased cystic fibrosis transmembrane conductance regulator (CFTR) function and virulence factors acquired by the bacteria." (PMID 21909403, 2011). "Thus, increasing COMMD1 expression may provide an approach to simultaneously inhibit ENaC absorption and enhance CFTR trafficking, two major issues in cystic fibrosis." (PMID 21483833, 2011). "Cystic fibrosis is one of the most common genetic disorders, caused by mutations in the CFTR gene, coding for the Cystic Fibrosis Transmembrane Conductance Regulator (CFTR) protein." (PMID 20868481, 2010). "However, HE3286 was found to be safe in the CFTR -/- male mouse model of cystic fibrosis." (PMID 21034489, 2010). "Ad5/F35 expressing a GFP-tagged CFTR transgene, displayed superior transduction to Ad5-GFP-CFTR in cystic fibrosis and non-CF human airway epithelial cells and restored chloride channel function." (PMID 21994621, 2010). "The absence of a functional ATP Binding Cassette (ABC) protein called the Cystic Fibrosis Transmembrane Conductance Regulator (CFTR) from apical membranes of epithelial cells is responsible for cystic fibrosis." (PMID 18463704, 2008). "Children with CFTR mutations may present with recurrent pancreatitis, lacking any other signs or symptoms of cystic fibrosis." (PMID 18501000, 2008). "One of the hurdles in gene therapy for CF is the necessity of regulating cystic fibrosis transmembrane conductance regulator (CFTR) gene expression in the appropriate cell types in the airway." (PMID 17604456, 2007). "The responsible gene has been identified as CFTR (cystic fibrosis transmembrane conductance regulator), and the vast majority of CF patients carry a deletion of phenylalanine from position 508 (ΔF508; Refs." (PMID 9488705, 1998). "There is limited data on how having a dedicated CF-GI clinic and cystic fibrosis transmembrane conductance regulator (CFTR) modulators may affect rates of GI complications." (PMID 40720490, 2025). "In recent years, life expectancy for patients with cystic fibrosis has markedly improved, due to innovative, effective treatment by CFTR (cystic fibrosis transmembrane conductance regulator) modulators." (PMID 40362587, 2025). "Interestingly, bovine PMT shares with Cystic Fibrosis the same pathogenetic mechanism of type II mutants of the Cystic Fibrosis Transmembrane Regulator (CFTR), which give rise to folding-defective proteins, affecting trafficking." (PMID 41206505, 2025). "Elexacaftor/tezacaftor/ivacaftor (ETI) cystic fibrosis transmembrane conductance regulator (CFTR) modulator therapy has led to rapid and substantial improvements in cystic fibrosis airway disease." (PMID 41212059, 2025). "In studies conducted prior to the introduction of cystic fibrosis transmembrane conductance regulator (CFTR) modulator therapy, children with CF showed an increased ventilation and perfusion impairment compared to healthy controls, especially those having frequent pulmonary exacerbations." (PMID 40766916, 2025). "Pharmacological rescue of F508del-CFTR by the triple combination CFTR modulator therapy elexacaftor/tezacaftor/ivacaftor (ETI) leads to unprecedented clinical benefits in patients with cystic fibrosis." (PMID 40261705, 2025).
cystic fibrosis (continued). "Then we further reveal how misfolding of different CFTR variants in Cystic Fibrosis disturbs these conformational changes even upon treatment with current approved drugs and suggest possibilities to stabilize misfolded CFTR variants not or less responsive to these drugs such as N1303K CFTR." (PMID 41258017, 2025). "A potential explanation for the apparent reduced efficacy of nebulized hypertonic saline in patients with PCD compared to those with CF is the presence of a functional cystic fibrosis transmembrane conductance regulator (CFTR) chloride channel in the PCD airway." (PMID 40171169, 2025). "Background/Objectives: The increasing use of statins in people with cystic fibrosis necessitates the investigation of potential drug–drug interactions (DDI) of statins with cystic fibrosis transmembrane conductance regulator (CFTR) modulators, including elexacaftor, tezacaftor, and ivacaftor (ETI)." (PMID 40142982, 2025). "Cystic fibrosis is an autosomal recessive disorder characterized by the absence ordysfunction of the CF transmembrane conductance regulator (CFTR) pro- tein due tomutations in the CFTR gene." (PMID 40145819, 2025). "CF is caused by mutations in the cystic fibrosis transmembrane conductance regulator (CFTR) gene, which encodes an anion channel essential for the normal function of many epithelial tissues." (PMID 40136707, 2025). "Infants who have a positive newborn screen but do not meet the formal diagnostic criteria for CF can receive an indeterminate diagnosis known as cystic fibrosis transmembrane conductance regulator (CFTR)-related metabolic syndrome (CRMS) or CF screen positive, inconclusive diagnosis (CFSPID)." (PMID 40843902, 2025). "It is characterized by high expression of the cystic fibrosis transmembrane conductance regulator (CFTR) and further ion transporters, and a role in the pathogenesis of cystic fibrosis has been proposed." (PMID 40888895, 2025). "CF genetic testing, approximately 12 years later, found no identifiable cystic fibrosis transmembrane conductance regulator (CFTR) variants." (PMID 41383369, 2025). "Given the low rates of pathogenetic CFTR mutations in Bangladeshi populations and our sequencing results from the large subset, we do not anticipate that we missed ascertaining genetic diagnoses of cystic fibrosis among the individuals who did not undergo sequencing." (PMID 40333927, 2025). "Ion channel activities were measured as short-circuit currents (Isc) of ENaC and CFTR in BMI1-transduced PCD airway epithelial cells and were compared to BMI1-transduced NHBE and cystic fibrosis cells (CFBE cells)." (PMID 41064994, 2025). "Defective CFTR (cystic fibrosis transmembrane conductance regulator) is pathognomonic for cystic fibrosis, which is characterized by an accumulation of tenacious secretions in pulmonary airways, as well as by abnormal ductal secretions in other organs, including the pancreas and prostate." (PMID 40362587, 2025). "In contrast, CF cell cultures (OS-344) showed little to no detectable CFTR expression, consistent with the known CFTR deficiency in cystic fibrosis." (PMID 40806745, 2025). "Such experiments are frequently used to evaluate the activity of the cystic fibrosis transmembrane conductance regulator (CFTR), a cAMP‐activated chloride channel that is defective in cystic fibrosis, one of the most frequent genetic diseases." (PMID 40047394, 2025). "The Cystic Fibrosis Foundation recommends that CF newborn screening algorithms should not limit CFTR variant detection to the F508del variant or variants included in the ACMG-23 panel." (PMID 40265445, 2025). "Cystic fibrosis was once a fatal disease of childhood, but with advances in combination CF transmembrane conductance regulator (CFTR) modulator therapies, children born with CF between 2019 and 2023 have a median predicted life expectancy of 61 years, nearly doubling over the past two decades." (PMID 41147257, 2025).